ENSG00000290474 (novel transcript)
Synonyms: GUSBL1; SMA3-L; SMAC3L; SMAC3L2; b55C20.1; bA239L20.1; bA239L20.5; bGLU-Lp; GUSBP2
Gene: Long non-coding RNA gene on chromosome 6 (26,813,826 to 26,964,603, reverse strand). Ensembl gene ENSG00000290474.
Gene Ontology:
Molecular function: triplet codon-amino acid adaptor activity
Biological process: translation